MDK (midkine)
Description:
Secreted protein that functions as a cytokine and growth factor and mediates its signal through cell-surface proteoglycan and non-proteoglycan receptors. Binds cell-surface proteoglycan receptors via their chondroitin sulfate (CS) groups. Thereby regulates many processes like inflammatory response, cell proliferation, cell adhesion, cell growth, cell survival, tissue regeneration, cell differentiation and cell migration. Participates in inflammatory processes by exerting two different activities. Firstly, mediates neutrophils and macrophages recruitment to the sites of inflammation both by direct action by cooperating namely with ITGB2 via LRP1 and by inducing chemokine expression. This inflammation can be accompanied by epithelial cell survival and smooth muscle cell migration after renal and vessel damage, respectively. Secondly, suppresses the development of tolerogenic dendric cells thereby inhibiting the differentiation of regulatory T cells and also promote T cell expansion through NFAT signaling and Th1 cell differentiation. Promotes tissue regeneration after injury or trauma. After heart damage negatively regulates the recruitment of inflammatory cells and mediates cell survival through activation of anti-apoptotic signaling pathways via MAPKs and AKT pathways through the activation of angiogenesis (By similarity). Also facilitates liver regeneration as well as bone repair by recruiting macrophage at trauma site and by promoting cartilage development by facilitating chondrocyte differentiation (By similarity). Plays a role in brain by promoting neural precursor cells survival and growth through interaction with heparan sulfate proteoglycans (By similarity). Binds PTPRZ1 and promotes neuronal migration and embryonic neurons survival. Binds SDC3 or GPC2 and mediates neurite outgrowth and cell adhesion. Binds chondroitin sulfate E and heparin leading to inhibition of neuronal cell adhesion induced by binding with GPC2. Binds CSPG5 and promotes elongation of oligodendroglial precursor-like cells (By similarity). Also binds ITGA6:ITGB1 complex; this interaction mediates MDK-induced neurite outgrowth. Binds LRP1; promotes neuronal survival. Binds ITGA4:ITGB1 complex; this interaction mediates MDK-induced osteoblast cells migration through PXN phosphorylation. Binds anaplastic lymphoma kinase (ALK) which induces ALK activation and subsequent phosphorylation of the insulin receptor substrate (IRS1), followed by the activation of mitogen-activated protein kinase (MAPK) and PI3-kinase, and the induction of cell proliferation. Promotes epithelial to mesenchymal transition through interaction with NOTCH2. During arteriogenesis, plays a role in vascular endothelial cell proliferation by inducing VEGFA expression and release which in turn induces nitric oxide synthase expression. Moreover activates vasodilation through nitric oxide synthase activation (By similarity). Negatively regulates bone formation in response to mechanical load by inhibiting Wnt/beta-catenin signaling in osteoblasts (By similarity). In addition plays a role in hippocampal development, working memory, auditory response, early fetal adrenal gland development and the female reproductive system (By similarity).
Synonyms: MK; ARAP; NEGF2; FLJ27379
Tractability: Antibody: its Gene Ontology location is reachable by antibodies, with high confidence; UniProt places it where antibodies can reach, with medium confidence; UniProt predicts a signal peptide or a membrane-spanning region. PROTAC: a small molecule that binds it is known.
Target class: Secreted protein
Gene: Protein-coding gene on chromosome 11 (46,380,756 to 46,383,837, forward strand). Ensembl gene ENSG00000110492.
Subcellular location: Secreted
Subcellular location (Human Protein Atlas): Vesicles; Predicted to be secreted
Pathways (Reactome):
Signal Transduction: MDK and PTN in ALK signaling; NOTCH2 Activation and Transmission of Signal to the Nucleus; Signaling by ALK
Gene Ontology:
Molecular function: heparan sulfate binding; heparin binding; protein binding; chondroitin sulfate binding; growth factor activity
Biological process: intracellular signal transduction; leukocyte chemotaxis involved in inflammatory response; negative regulation of cardiac muscle cell apoptotic process; negative regulation of neuron apoptotic process; negative regulation of regulatory T cell differentiation; positive regulation of blood vessel branching; positive regulation of cell adhesion; positive regulation of cell migration; positive regulation of epithelial to mesenchymal transition; positive regulation of inflammatory response; positive regulation of interleukin-12 production; positive regulation of keratinocyte proliferation; positive regulation of leukocyte cell-cell adhesion; positive regulation of macrophage chemotaxis; positive regulation of neuron migration; positive regulation of neuron projection development; positive regulation of oligodendrocyte differentiation; positive regulation of smooth muscle cell chemotaxis; adrenal gland development; cell differentiation; cytoskeleton organization; estrous cycle; glial cell projection elongation; negative regulation of canonical Wnt signaling pathway; negative regulation of cell adhesion; and 37 more
Cellular component: extracellular matrix; extracellular region
Genetic constraint (gnomAD): Loss-of-function variants: 16 observed, 14.06 expected, observed/expected ratio (o/e) 1.14, 90% interval 0.77 to 1.7. The upper end of that interval is the gene's LOEUF score, 1.7, which puts it in group 6 of 6, group 1 being the genes least tolerant of losing a copy. Missense variants: 173 observed, 172.1 expected, observed/expected ratio (o/e) 1.01, 90% interval 0.89 to 1.14. Synonymous variants: 84 observed, 70.57 expected, observed/expected ratio (o/e) 1.19, 90% interval 1 to 1.43.
Homologues: Orthologues: chimpanzee MDK (100% identical), macaque MDK (100% identical), pig MDK (94% identical), dog MDK (89% identical), guinea pig MDK (87% identical), rat Mdk (87% identical), mouse Mdk (86% identical), tropical clawed frog mdk (61% identical), zebrafish mdka (60% identical), zebrafish mdkb (54% identical). Paralogues in human: PTN (48% identical).
Diseases named in the same sentence as MDK in open-access papers:
MDK is named in the same sentence as 210 diseases in open-access papers, as found by Europe PMC text mining. Sharing a sentence is not in itself a finding about the gene and the disease. The quoted sentences say what the papers report.
glioma (33 papers, 2013 to 2026). A benign or malignant brain and spinal cord tumor that arises from glial cells (astrocytes, oligodendrocytes, ependymal cells). "The results showed that compared with adjacent tissues, MDK and c‐Myc were significantly upregulated in glioma tissues, and the expression of MDK and c‐Myc genes was associated with the occurrence of glioma." (PMID 40468625, 2025). "In summary, existing literature indicates that MDK is widely regarded as an important biomarker in gliomas, with its overexpression closely associated with tumour proliferation, invasiveness, and chemoresistance." (PMID 40468625, 2025). "Overall, our study confirmed earlier findings of increased MDK expression in gliomas, proportional to the tumor grade, as well as its association with poor survival in GBM with a diverse 1000 + patient cohort." (PMID 40835683, 2025). "MDK and c‐Myc have been implicated as important regulatory factors in the growth and progression of glioma." (PMID 40468625, 2025). "Nine unfavorable prognosis-associated and six favorable prognosis-associated proteins were detected in our proteome data, in which MDK was the only protein associated with unfavorable prognosis in glioma patients." (PMID 31811117, 2019). "Our study also indicates that MDK expression in IDHwildtype gliomas correlates with tumor grade, potentially reflecting selective pressure favoring the ENST00000395566 isoform, and that high midkine expression is associated with a poor prognosis in IDHwildtype grade IV gliomas (GBM)." (PMID 40835683, 2025). "In brain tumors both MDK and PTN might be useful as early diagnostic and independent prognostic markers, as MDK overexpression correlates with the rapid progression of astrocytomas and a poor survival outcome in high-grade gliomas." (PMID 38098484, 2023). "To further clarify the regulatory relationship between MDK and c‐Myc, we transfected MDK gene‐specific siRNA into glioma cells to silence the expression of the MDK protein." (PMID 40468625, 2025). "A series of experiments showed that c‐Myc restoration partially restored the effects of MDK gene knockout on cell proliferation and invasion, indicating that MDK influences the malignant progression of glioma cells through the c‐Myc/Wnt pathway." (PMID 40468625, 2025). "Our studies have found that the expression level of the MDK gene is significantly upregulated in glioma, confirming the correlation between MDK gene expression changes and glioma." (PMID 40468625, 2025). "First, the expression of MDK at the protein level was detected in multiple glioma cell lines, including U118MG, BT325, U251, SF126, SHG44, U87, and the normal glial cell line HEB." (PMID 40468625, 2025). "CCK8 assay, EdU assay, and clonal formation experiment indicated that reducing MDK levels suppressed the proliferation of glioma cells while increasing MDK levels enhanced their proliferation." (PMID 40468625, 2025). "This study provided preliminary evidence of the role of the MDK gene in the development and progression of glioma, providing a theoretical basis for the identification of targets for gene therapy." (PMID 40468625, 2025). "The findings indicated that knocking down MDK had a notable hindering impact on the development of tumours in glioma cells in vivo." (PMID 40468625, 2025). "In this study, the levels of midkine (MDK) and c‐Myc expression in glioma patient samples downloaded from TCGA were analyzed." (PMID 40468625, 2025). "We showed that gliomas express and secrete MDK in excessive quantities with higher expression in IDHwildtype gliomas." (PMID 40835683, 2025). "The research demonstrated that MDK can control the Wnt/β‐catenin pathway in glioma cells by interacting with the oncogene c‐Myc." (PMID 40468625, 2025).
glioma (continued). "Given that retinoic acid signaling is commonly overactivated in high-grade gliomas and correlates with adverse prognosis, our findings suggest a plausible involvement of MDK in mediating these effects, warranting further mechanistic investigation." (PMID 40835683, 2025). "Immunofluorescence and immunohistochemistry findings indicated a notable increase in MDK expression in glioma tumour tissues compared with adjacent non‐tumour tissues." (PMID 40468625, 2025). "Further preclinical and clinical studies are warranted to validate the therapeutic potential of targeting the MDK/c‐Myc complex in glioma treatment." (PMID 40468625, 2025). "This elucidation not only enriches the understanding of MDK's role in glioma biology but also identifies new potential targets for future clinical treatments." (PMID 40468625, 2025). "The findings indicate that inhibiting the Wnt/β‐catenin pathway can decrease the oncogenic impacts of MDK in glioma." (PMID 40468625, 2025). "The discovery of the MDK/c‐Myc axis provided novel therapeutic targets for drug resistance in gliomas." (PMID 40468625, 2025). "In glioma, MDK secreted by GBM cells drives macrophage polarization toward the M2 phenotype by activating receptors on macrophages, leading to the secretion of cytokines such as CXCL1 and thereby fostering an immunosuppressive environment." (PMID 41246334, 2025). "Based on these findings, this study demonstrated that silencing MDK reduces the resistance of glioma cells to TMZ treatment." (PMID 40468625, 2025). "Combining ACT001 with temozolomide synergistically inhibits tumour growth and progression, offering a promising therapeutic strategy for glioma patients, particularly those with high MDK expression." (PMID 40468625, 2025). "The results of animal experiments indicate that targeted blockade of the MDK signaling pathway can reverse the formation of an immunosuppressive microenvironment, slow the malignant progression of gliomas, and prolong the prognosis of mice." (PMID 40527884, 2025). "In accordance with the WHO pathological grading, the expression levels of c-Fos and MDK in glioma increased with the grade." (PMID 40527884, 2025). "To further investigate the effect of targeted regulation of the MDK signaling pathway in glioblastoma on the growth and prognosis of intracranial tumors, we established a mouse glioma intracranial model." (PMID 40527884, 2025). "We characterized MDK expression patterns in a wide range of gliomas from ethnically different cohorts and revealed coordinated changes in its expression and isoform proportions." (PMID 40835683, 2025). "Co‐expression analysis of TCGA glioma sequencing data showed a co‐expression trend between MDK and c‐Myc expression levels in glioma tissues." (PMID 40468625, 2025). "Our findings, focusing on the MDK/c‐Myc complex, are complementary to these reports and extend the potential spectrum of MDK as a therapeutic target in glioma." (PMID 40468625, 2025). "First, the expression levels of c-Fos and MDK in common glioma cell lines were detected by Western blotting and qPCR, and based on the results, three cell lines, U87, U251 and T98, were selected for subsequent experiments." (PMID 40527884, 2025). "In studying the role of MDK in the advancement of glioma, in vitro experiments were performed, which demonstrated that reducing MDK levels hindered the proliferation and migration of glioma cells." (PMID 40468625, 2025). "This study revealed that MDK impacted the Wnt signalling pathway by ubiquitinating c‐Myc, thereby influencing the resistance of glioma cells to TMZ." (PMID 40468625, 2025). "The disruption of the interaction between MDK and c‐Myc has potential therapeutic effects on glioma." (PMID 40468625, 2025). "After conducting Kaplan–Meier plotter analysis, the patients with glioma were categorized into the high‐ and low‐expression groups based on the median MDK expression level." (PMID 40468625, 2025).
glioma (continued). "To investigate MDK’s function in glioma, we integrated four RNA-Seq datasets into a harmonized cohort of 1,017 adult gliomas, including 256 GBM samples." (PMID 40835683, 2025). "Analysis of a large number of different glioma cases in the database showed that MDK was significantly upregulated in glioma cases than in the control tissues." (PMID 40468625, 2025). "To assess its prognostic significance, we have performed Kaplan-Meier univariate Cox regression analyses in gliomas using MDK expression as an overall survival (OS) predictor." (PMID 40835683, 2025). "ACT001 facilitated the degradation of c‐Myc by focusing on the MDK/c‐Myc complex and controlled the Wnt/β‐catenin signalling pathway via MDK, ultimately halting the advancement of glioma." (PMID 40468625, 2025). "Given that almost all patients with glioma eventually develop drug resistance, the discovery of MDK targets and the activity of ACT001 are of high clinical value." (PMID 40468625, 2025). "ACT001 disrupts the MDK/c‐Myc complex, enhancing c‐Myc ubiquitination and overcoming temozolomide resistance in glioma." (PMID 40468625, 2025). "In this research, plasmid transfection was utilized to increase the expression level of MDK in glioma cells, and stable cell lines that expressed MDK were selected through hygromycin screening." (PMID 40468625, 2025). "Using BALB/c nude mice, we established a glioma xenograft model and found that MDK overexpression significantly increased tumour volume and weight." (PMID 40468625, 2025). "Our study found that among all patients with glioma or among glioma patients classified into high and low‐grade subtypes based on malignancy, those with high MDK mRNA expression had shorter survival and worse prognosis compared with those with low expression." (PMID 40468625, 2025). "The PLA results demonstrate distinct punctate signals indicating the physical proximity of endogenous MDK and c‐Myc proteins within glioma cells." (PMID 40468625, 2025). "We found that MDK expression increases with tumor grade in IDHwildtype gliomas, accompanied by a shift in isoform proportions favoring the canonical MDK transcript." (PMID 40835683, 2025). "Recent reports suggest that ALK and its ligand, MIDKINE (MDK), promote the resistance of glioma cells to anticancer therapies such as TMZ." (PMID 38334610, 2024). "It has also been reported that the MDK gene can promote the proliferation of human cancer cells, such as gastric cancer cells and glioma cells." (PMID 38255198, 2024). "MDK induces cell proliferation, cancer stemness, and invasion in glioma cells resulting in temozolomide (TMZ) resistance." (PMID 37240085, 2023). "CD8+ T cells are a common type of T cells, and the CD8+ T cell family establishes a neuronal-immune-cancer axis through midkine activation to enhance favorable conditions for the growth of low-grade glioma." (PMID 37351101, 2023). "MDK/ALK receptor axis is also noted to maintain the self-renewal capacity of the glioma-initiating cells (GICs) by preventing the autophagic degradation of the transcription factor SOX9." (PMID 37240085, 2023). "Pharmacological targeting of the MDK/ALK axis with crizotinib effectively acts on the population of glioma-initiating cells (GIC) in vitro and in tumor xenografts." (PMID 35625997, 2022). "MDK is a secreted cytokine and heparin-binding factor that has been identified as a liquid biomarker in glioma and other tumors." (PMID 34502484, 2021).